IGF2 (insulin like growth factor 2)
Diseases named in the same sentence as IGF2 in open-access papers (continued):
Sharing a sentence is not in itself a finding about the gene and the disease.
leukemia (11 papers, 2005 to 2024). A malignant (clonal) hematologic disorder, involving hematopoietic stem cells and characterized by the presence of primitive or atypical myeloid or lymphoid cells in the bone marrow and the blood. "By mapping our fetal mouse pre-leukemic secretome to the human infant leukemia secretome, we observed the reversal of secretion of these proteins with the addition of IGF2 to the human leukemia cells." (PMID 38555405, 2024). "Because of this specific viability effect of IGF2 on infant leukemia cells, we further investigated the potential effects to their secretome." (PMID 38555405, 2024). "The IGF2/IGF1R/NANOG signaling pathway has important functions in leukemia stem cell proliferation, and the knockdown of NANOG induces cell cycle arrest and apoptosis." (PMID 33336042, 2020). "IGF2BP3 plays a critical role in regulating cell proliferation via an IGF2-dependent pathway in K562 leukemia cells." (PMID 28771592, 2017). "Finally, miR-223 was found to inhibit cellular growth in leukemia cells by targeting Insulin-Like Growth Factor 2 (IGF2)." (PMID 27179712, 2016). "IGF2BP3 (alias IMP3), represses translation of IGF-2 during late embryonic development in mice and humans, and has been shown to promote the translation of IGF-2 leader 3 mRNA in a cell model of leukemia." (PMID 23936243, 2013). "Interestingly, the infant leukemia cell lines KOPN-8 and THP-1 both showed decreased viability in the presence of IGF2, while adult leukemia cells (Mono-Mac-6 and NOMO-1) were unaffected." (PMID 38555405, 2024). "Critically, differential dependency on the Igf2/Igf2r and Fn1/VLA-4 axes upon initiation of fetal- and adult-origin MLLr leukemia may represent an opportunity for targeting ontogeny-specific vulnerabilities in in utero-derived and adult-onset leukemia." (PMID 38555405, 2024). "After GO analysis of the seventy-four genes, six secreted cytokines related to cell cycle, proliferation and apoptosis including CSF2, CTF1, FGF2, IGF2, HGF and LIF were selected for PCR verification and FGF2 was confirmed to be significantly up-regulated in leukaemia mice derived MSCs." (PMID 36333298, 2022).
mesenchymal tumors (11 papers, 2006 to 2026). "IGF-2-mediated hypoglycemia has been described in a wide variety of epithelial and mesenchymal tumours." (PMID 38432069, 2024). "In a leiomyoma, IGF2 was found to be the major driver of tumor growth, and IGF2 was found to be the most overexpressed gene in colorectal neoplasia and highly expressed in mesenchymal tumors." (PMID 29758070, 2018).
osteoporosis (11 papers, 2010 to 2025). A condition of reduced bone mass, with decreased cortical thickness and a decrease in the number and size of the trabeculae of cancellous bone (but normal chemical composition), resulting in increased fracture incidence. "Besides, we determined the levels of miR-33a-3p and IGF2 in the serum of osteoporosis patients and explored the potential associations with BMD." (PMID 37415192, 2023). "The level of miR-33a-3p was substantially higher and IGF2 expression was memorably lower in the serum of osteoporosis patients than that in healthy volunteers." (PMID 37415192, 2023). "Our data suggested that miR-33a-3p was over-expressed and IGF2 was down-regulated in the serum of osteoporosis patients, as exposed to control group." (PMID 37415192, 2023). "Taken these data together, miR-33a-3p/IGF2 was evidenced to be involved in the progression of osteoporosis." (PMID 37415192, 2023). "MiR-33a-3p was up-regulated and IGF2 was down-expressed in the serum of osteoporosis patients, as exposed to the healthy control group." (PMID 37415192, 2023). "Crucially, in an analogous study, miR-483-5p was upregulated, and IGF2 downregulated in bone tissues and serum samples isolated from osteoporosis patients." (PMID 35011442, 2021). "It was reported that miR-483 is involved in the pathogenesis of Duchenne muscular dystrophy, alcohol-induced osteonecrosis of femoral head, and osteoporosis by targeting insulin-like growth factor-2 (IGF-2) through inhibiting osteoblast differentiation." (PMID 33801675, 2021). "IGF2 disorders result in various diseases such as growth retardation, diabetes, neurodegenerative diseases, atherosclerosis, osteoporosis and cancer." (PMID 33266436, 2020). "After adjusting for age, significant differences were seen between groups with respect to levels of Ca, Mn, Cd and IGF-2 (P values = .04.007.005, and .001, respectively), all of which were higher in the osteoporosis group." (PMID 32629669, 2020). "Therefore, to clarify the expression difference of miR-33a-3p and IGF2 in the osteogenic differentiation of hBMSCs has guiding significance for the development of osteoporosis." (PMID 37415192, 2023). "Besides, we evaluated the levels of miR-33a-3p and IGF2 in the serum of osteoporosis patients." (PMID 37415192, 2023). "As a member of the insulin-like growth factor family, IGF2 is widely involved in many physiological and metabolic processes in the body and plays an important role in cancer development, neuromodulation, diseases of glucose metabolism, osteoporosis, muscle development and fat deposition." (PMID 33266436, 2020). "For example, Ostf1 (osteoclast stimulation factor 1) can promote osteoporosis, Tgm2 is involved in negative artery remodeling, and IGF2 can contribute to senescence of MSCs." (PMID 32727501, 2020). "In osteoporosis, only upregulation of miR-483-5p has a negative effect on IGF2 and inhibits osteoblast differentiation by combining with the 5′-UTR of the fetal IGF2 promoter transcript." (PMID 31831773, 2019).
Parkinson disease (11 papers, 2008 to 2025). A progressive degenerative disorder of the central nervous system characterized by loss of dopamine producing neurons in the substantia nigra and the presence of Lewy bodies in the substantia nigra and locus coeruleus. "IGF2 deficiency has been associated with neurodegenerative diseases such as Alzheimer’s, Parkinson’s, and Huntington’s diseases, possibly contributing to cognitive decline and muscle weakness in frail patients." (PMID 41463319, 2025). "IGF2 deficiency is associated with certain brain diseases, including AD, Parkinson’s disease, Huntington’s disease, and amyotrophic lateral sclerosis." (PMID 41225538, 2025). "Perturbation in IGF2/IGF2R signaling has been associated with autophagy impairment in several human diseases (such as Parkinson’s disease and cancer) and similar evidence has been observed in mice brains after treatment with IGF2." (PMID 38612397, 2024). "We also examined expression of H19, IGF2, and CDKN1C in laser-captured dopamine neurons, identified on the basis of neuromelanin presence, from a series of human postmortem RNA samples from human cases of Parkinson's disease and controls." (PMID 18183302, 2008).
adrenocortical adenomas (10 papers, 2008 to 2025). "One study looking at 67 samples of ACC and 64 samples of adrenal adenomas showed tissue expression of IGF-2 by immunohistochemistry (IHC) at 92.5% and 54.7%, respectively." (PMID 40270996, 2025). "The expression of IGF2 in adrenocortical adenocarcinoma is higher than that in adrenocortical adenoma." (PMID 35983531, 2022). "The abnormal methylation at the IGF2/H19 locus is common in adrenocortical carcinomas and methylation patterns of IGF2 regulatory regions has been proposed to discriminate ACC from adrenal adenomas with high diagnostic accuracy." (PMID 33260476, 2020). "Clinical, histopathological, and molecular features of adrenal adenoma, IGF2-low carcinoma, and IGF2-high carcinoma." (PMID 25089899, 2014). "IGF2 overexpression is found in almost all adrenal carcinomas compared with adrenal adenomas or healthy adrenals." (PMID 22952916, 2012). "Higher somatic IGF-2 expression has been seen in ACC when compared with benign adrenal adenomas." (PMID 40270996, 2025). "However, the differential diagnosis of adrenocortical adenocarcinoma and adrenocortical adenoma cannot be accurately performed by only using IGF2 as an indicator." (PMID 35983531, 2022). "This study aimed to investigate IGF1R and IR expression and localisation, including the expression of IR isoforms, in ACC and adrenocortical adenomas (ACA), and their role in IGF2-driven proliferation." (PMID 40038716, 2025). "In sporadic adrenal tumours, IGF2 is overexpressed in 80–90% of ACC but not in adrenocortical adenomas (ACA)." (PMID 22952916, 2012). "IGF2 immunohistochemistry expression was evaluated in ACC (n = 13), non-functioning adrenocortical adenoma (ACAn) (n = 14), and N-AG (n = 9)." (PMID 31378849, 2019). "Insulin-like growth factor 2 (IGF2) protein expression is usually 8–80 fold higher in ACC when compared to normal adrenal glands (N-AG) or adrenocortical adenomas (ACA), despite the fact that the biological features of high vs. low IGF2 expressing ACC have not yet been well characterized." (PMID 31378849, 2019).
Cirrhosis (10 papers, 2003 to 2021). A chronic disorder of the liver in which liver tissue becomes scarred and is partially replaced by regenerative nodules and fibrotic tissue resulting in loss of liver function. "Changes in IGF2 expression have been implicated in the development ofchronic liver diseases including simple steatosis, cirrhosis and even HCC." (PMID 33988719, 2021). "According to many studies, IGF2 levels decrease in cirrhosis, compared to normal individuals and increase in HCC." (PMID 34714420, 2021). "In patients with cirrhosis, there is a significant reduction in serum IGF2 levels, in relation to healthy people." (PMID 29702590, 2018). "IGF2 has been reported to be overexpressed in advanced stages of liver disease, i.e., cirrhosis and HCC." (PMID 27199763, 2016). "All of the 10 specimens with cirrhosis related to HBV or HCV infection were among those cases with clusters of hepatocytes overexpressing IGF-2, and altered M6P/IGF-2R staining patterns were common to all cirrhotic specimens." (PMID 12618883, 2003). "In one case of HCV-related cirrhosis small groups of bile duct epithelial cells within fibrotic septa displayed significantly increased expression of IGF-2 as well." (PMID 12618883, 2003). "IGF2 has been described to be overexpressed in cirrhosis and HCC." (PMID 27199763, 2016). "We therefore hypothesize that this high IGF1+IGF2/IGFBP3 molar ratio, resulting in high total (IGF1+IGF2) bioavailability, could slow down the evolution form HS to fibrosis or cirrhosis." (PMID 25117570, 2014). "The pattern observed with normal liver samples was also found in specimens with cirrhosis of nonviral aetiology with one exception: one case with autoimmune hepatitis-related cirrhosis showed occasional groups of hepatocytes with moderately increased IGF-2-specific labelling." (PMID 12618883, 2003). "IGF2 was up-regulated in hepatitis B virus-related HCC, and IGF2 methylation decreased during progression from cirrhosis to HCC34,35." (PMID 32372053, 2020). "The IGF2 had a sensitivity of 80%, and specificity of 73.3% in differentiating HCC from cirrhosis." (PMID 34714420, 2021). "High focal expression of IGF2 RNA was found in some hepatocytes of all livers with HBV- or HCV-induced cirrhosis, but in only one of the cirrhoses with a nonviral etiology." (PMID 29702590, 2018). "However, in hepatitis and cirrhosis, IGF-2 expression is increased, owing to reactivation of fetal promoters that induce Igf2 gene transcription." (PMID 25052889, 2014). "In HCV-related cirrhosis, HCV replication was positively correlated with overexpression of IGF-2." (PMID 12618883, 2003). "In addition to the focal upregulation of IGF-2, we observed reduced M6P/IGF-2R-specific immunostaining in cirrhosis when compared to normal liver." (PMID 12618883, 2003). "High focal levels of IGF-2 RNA were found in some hepatocytes of all livers with HBV- or HCV-induced cirrhosis (n=10), but in only one of the cirrhoses with nonviral aetiology (n=8)." (PMID 12618883, 2003). "This has prompted us to use in situ hybridisation and immunohistology to assess cellular levels of IGF-2 transcripts and M6P/IGF-2R antibody staining patterns in cases of cirrhosis of different aetiologies without morphological evidence of premalignant or malignant changes." (PMID 12618883, 2003).
esophageal squamous cell carcinoma (10 papers, 2012 to 2024). Esophageal squamous cell carcinoma (ESCC) is a type of esophageal carcinoma (EC) that can affect any part of the esophagus, but is usually located in the upper or middle third. "In the context of acquired resistance, it has been shown that the c-Jun/Axl axis and an upregulation of insulin growth factor 2 (IGF2) are associated with a poor response to PI3Kα blockage in HNSCC and esophageal squamous cell carcinoma cells." (PMID 38286037, 2024). "A study found miR-483-5p to be expressed in esophageal squamous cell carcinoma (ESCC), with low levels of IGF2 promoter methylation (associated with increased IGF2 expression) and proposed a permissive level for IGF2 promoter methylation towards the observed miR-483-5p tumor suppressing effects." (PMID 37371750, 2023). "miR-6759-5p was found to target IGF2 and is suppressed by a long-non-coding RNA (lnc-MCEI), which stimulates IGF2-mediated chemosensitivity in esophageal squamous cell carcinoma (ESCC)." (PMID 37371750, 2023). "Alternatively, in esophageal squamous cell carcinoma, H19 CTCF-binding site 6 (CBS6) hyper-methylation correlates with overexpression of IGF2 in patients." (PMID 35459174, 2022). "Here we identified lncRNA ENST00000441932 as an oncogenic lncRNA in esophageal squamous cell carcinoma (ESCC) and named lnc-MCEI (lncRNA mediated the chemosensitivity of ESCC by regulating IGF2)." (PMID 33061807, 2020). "LOI of the IGF2 has also been found in some adult somatic tumors including colorectal cancer (CRC), renal cell carcinoma (RCC), stomach adenocarcinoma (STAD), and esophageal squamous cell carcinoma (ESCC)." (PMID 38812777, 2024).
Ewing sarcoma (10 papers, 2012 to 2024). A small round cell tumor that lacks morphologic, immunohistochemical, and electron microscopic evidence of neuroectodermal differentiation. "Previous analysis of autocrine signaling circuits in Ewing sarcoma identified the activity of IGF1 (IGF2)/IGF1R signaling in both Ewing sarcoma cells and patient tissues." (PMID 38906855, 2024). "HMGA2, IGF2BP2, IGF2BP3, and IGF2 were confirmed to be significantly overexpressed in CDS-derived cell lines compared with Ewing sarcoma–derived cell lines." (PMID 34903601, 2022). "In Ewing sarcoma, transcriptional up-regulation and autocrine activation of the IGF2/IR-A axis represents a major mechanism of resistance to anti-IGF1R agents." (PMID 33673232, 2021). "In Ewing sarcoma, this oncofetal protein can mediate IGF1R loss and subsequent compensatory IRA and IGF2 activation in some cell lines." (PMID 33260481, 2020). "Interestingly, in Ewing sarcoma cell lines, IGF2BP3-mediated IGF1R loss is compensated by the activation of an IR-A/IGF2 autocrine loop, which determines higher sensitivity to the dual IGF1R/IR inhibitor OSI-906." (PMID 33673232, 2021). "Indeed, stimulation of serum-starved PDX-CDS or PDX-Ewing sarcoma cells with IGF2 led to ERK activation in Ewing sarcoma cells but not in CDS cells, while AKT activation was observed in both CDS and Ewing sarcoma cells." (PMID 34903601, 2022). "qRT-PCR confirmed that CDS specimens exhibited significantly elevated expression of HMGA2, IGF2BP2, IGF2BP3, and IGF2, but not HMGA1, compared with Ewing sarcoma specimens." (PMID 34903601, 2022). "IGF2 was shown to be specifically overexpressed in ARMS compared to Ewing’s sarcoma cell lines, which is perhaps not surprising given that LOI of the IGF2 is seen in almost half of ARMS tumors." (PMID 23206814, 2012).
non-small cell lung carcinoma (10 papers, 2015 to 2024). A group of at least three distinct histological types of lung cancer, including non-small cell squamous cell carcinoma, adenocarcinoma, and large cell carcinoma. "Autocrine IGF2 induced resistance to taxol in BC cells, while in non-small-cell lung cancer cells, CAF-dependent activation of the IGF2-AKT-Sox2-ABCB1 signaling was associated with resistance to doxorubicin, which was reverted by IGF1R blockade." (PMID 36672737, 2023). "ITGA11 was found to enhance tumorigenicity of human non-small-cell lung cancer cells by regulating IGF2 expression in fibroblasts." (PMID 34257701, 2021). "Both genes have proven oncogenic effects, such as the role of acetylated STAT3-mediated activation of IGF2 transcription in HDI (Histone deacetylase inhibitors) resistance described in NSCLC (non-small-cell lung carcinoma)." (PMID 34198846, 2021). "Upregulation of IGF2anti-sense inhibits IGF2 in murine neurons and human non-small cell lung cancer (NCSLC) cell lines." (PMID 31231466, 2019). "In addition, the observed increase in histone acetylation levels in human non-small cell lung cancer cells and human lymphoma cells can promote the expression of DNMT1, cause hypermethylation at the ICR binding site of CTCF-H19/IGF2, and reduce the occupancy of CTCF at the ICR of H19/IGF2." (PMID 38584203, 2024). "In non-small cell lung cancer (NSCLC), circNDUFB2 also inhibits NSCLC progression by disrupting insulin-like growth factor 2 mRNA-binding proteins and activating anti-tumor immunity." (PMID 35464462, 2022).
type 1 diabetes (10 papers, 2010 to 2024). "IGFs (IGF1 and IGF2) expedite glucose metabolism with their availability modulated by IGF binding proteins, and function as prognostic factors for type 1 diabetes." (PMID 32694937, 2020).
brain tumors (9 papers, 2010 to 2024). "Efficient delivery of IGF2 blockade to the brain is critical to the therapeutic efficacy of oHSV for primary and metastatic brain tumors." (PMID 38853689, 2024). "We have also tested 48 pediatric brain tumors of different types with in situ hybridization for IGF2 expression." (PMID 20862257, 2010). "We have shown that pericytes play a crucial role in the development of metastatic brain tumors by secreting ECM proteins, which enhanced the adhesion of TN BCCs, and by secreting insulin-like growth factor 2, which had a pro-proliferative effect." (PMID 33671551, 2021). "Additionally, there was a significant positive correlation between expression of IGF2 and NFκB, GATA2 and STAT3 in brain tumor patients sampled in the CGGA dataset." (PMID 38853689, 2024).